FOXP3 (forkhead box P3)
Diseases named in the same sentence as FOXP3 in open-access papers (continued):
Sharing a sentence is not in itself a finding about the gene and the disease.
Sepsis (continued). "In addition, multiple clinical studies show that amplification of CD4+CD25+ Tregs and increased Foxp3 levels may increase risks of nosocomial infections or secondary infections in sepsis." (PMID 35281010, 2022). "Moreover, the different recovery rates between the memory and regulatory Foxp3+ CD4 T cell populations could suggest additional time-dependent mechanisms that control the ability of sepsis survivors to respond to secondary infection." (PMID 32903436, 2020). "One study showed that sialoadhesin (Sn) expressed by monocytic cells can bind to CD43 expressed on Foxp3+ Treg and negatively regulate their expansion, and thus future investigation of the frequency and localization of Sn+ monocytes during sepsis may yield important insights." (PMID 30226896, 2018). "In sepsis, age positively correlated with the percent of CD4+ cells that were regulatory (CD45RA+FoxP3+), r2 = 0.32, p=0.002." (PMID 39935482, 2025). "The sepsis cohort, compared to healthy, had a higher proportion on Day 1 of CD4+ T cells expressing regulatory markers (CD45RA+/FoxP3+) (22% vs 12% of CD4+, p=0.01)." (PMID 39935482, 2025). "Additionally, adiponectin enhances regulatory T cell (Treg) function by upregulating FOXP3 and IL-10 expression, promoting immune tolerance which could be beneficial in sepsis through limiting the uncontrolled immune activation that is characteristic of sepsis." (PMID 40652274, 2025). "The percentage of peripherally induced naïve regulatory T cells (CD3+CD4+CD25+FOXP3+CD45RA+ CD31-) was significantly higher in neonates developing sepsis compared to another group." (PMID 39072327, 2024). "At the same time, the frequency of RTE Treg (CD3+CD4+CD25+FOXP3+ CD45RA+CD31+) was considerably lower, suggesting that Treg cells are more peripherally induced in newborns developing sepsis." (PMID 39072327, 2024). "Our data show that IL-10 and Foxp3 are elevated in CD4+ T cells in the periphery of sepsis survivor mice as depicted by the % of IL-10+ CD4+ T cells and Foxp3+ CD4+ T cells." (PMID 37175808, 2023). "The synthetic cannabinoid WIN55212-2 exhibits in vivo protective and anti-inflammatory effects in LPS-induced sepsis by mechanisms depending on CB1- and PPARα-mediated autophagy induction and also promotes the generation of FOXP3+ Tregs." (PMID 34548620, 2022). "We found in sepsis that the A2aR antagonist ZM241385 inhibited Treg expansion, CTLA-4 and Foxp3 expression, secretion of IL-10 and TGF-β and inhibitory activity on T-cell proliferation." (PMID 36148230, 2022). "MDSCs have an immunosuppressive function by expanding FOXP3+ Tregs and inhibiting CD4+ T-cell proliferation in sepsis." (PMID 35720398, 2022). "In PH mice, TIGIT was upregulated on total CD4+ T cells, Foxp3+ Treg, CD4+ Foxp3– T conventional cells (Tconvs), and NK cells on days 2 and 3 after sepsis compared with sham controls." (PMID 34100383, 2021). "Another study in a sepsis model of Tregs confirmed that JNK/AP-1 signaling cascade contributes to the elevated expression of FOXP3 and controls FOXP3 promoter activity." (PMID 31340499, 2019). "It is very important that HD-IVIG increases the percentage of Foxp3 + T cells in premature infants, because the Foxp3 + Treg cell plays a role of immune tolerance, and the infusion of IVIG reduced the inflammation to external stimulation in severe sepsis." (PMID 29466960, 2018). "To address the impact of sepsis on natural Tregs, we subjected DEREG mice to CLP and measured the proportion of Foxp3+ cells in the CD4+ T cell population." (PMID 23724126, 2013). "Twenty-four hours after sepsis induction, the percentage of CD4+Foxp3+ splenocytes was significantly increased." (PMID 23724126, 2013). "The observed increase in Foxp3+ Treg proportion during early sepsis is primarily attributed to the extensive death of non-Treg cells." (PMID 40806563, 2025).
Sepsis (continued). "Our study showed elevated Foxp3/IL-10 levels and Treg cells in the CNS/periphery by the ITK inhibitor, which may counter the sepsis-mediated depression-like state in mice." (PMID 37175808, 2023). "During sepsis, IL-33 released by damaged cells initiates a signaling cascade through its receptor ST2 on M2 macrophages that favors the expansion of the highly suppressive TIGIT+FOXP3+T regulatory cells." (PMID 37604833, 2023). "Ex vivo cultured T cells with MDSCs in the Th0 condition (without the presence of any T-cell stimulant) showed increased expression of CD4+FOXP3+ (p = 0.044) in sepsis patients, but no such increased expression was observed in HCs and w/o sepsis patients." (PMID 35720398, 2022). "In conclusion, our results indicated that NC supplementation for 10 days in ICU patients with sepsis significantly decreased pro-inflammatory cytokines, MODS, and SOFA scores, the mRNA expression of NF-êB, NLRP-3, IFN-γ, and increased the expression of FOXP3." (PMID 36562037, 2022). "By blocking MDSC activity with nor-NOHA and l-NMMA, there was a significant decrease in CD4+FOXP3+ T cells (p = 0.014 and p = 0.045) in sepsis patients, but no such significant difference was observed in w/o sepsis patients and HCs." (PMID 35720398, 2022). "In light of this, we chose to initially determine how VISTA impacted sepsis-induced Treg polarization by comparing the CD4+Foxp3+ Treg populations in WT as opposed to VISTA-/- mice via flow cytometry." (PMID 35401514, 2022). "We found that FoxP3 was more expressed by treatment with high (10 ng/mL) than low dose (10 pg/mL) of IL-1β, raising a possibility of IL-1β induced CD4 T-cell differentiation to regulatory T cells in sepsis." (PMID 31323786, 2019). "Finally, we assess the role of regulatory T cells (TReg cells), defined as Foxp3+ CD25+ CD4+ cells, in the increased mortality observed in CD43-/- animals during sepsis." (PMID 30226896, 2018). "Interestingly, IL-7 treatment resulted in an immediate increase in the classical Foxp3+CD25+ Treg population, 1 week after sepsis induction." (PMID 29466409, 2018). "In human sepsis, the majority of data obtained on the role of leukocyte subsets in sepsis is confined to the peripheral blood, focusing primarily on the role of the immune-suppressing CD4+CD25+Foxp3+ regulatory T cells (Tregs), impaired monocyte HLA-DR expression, and lymphocyte apoptosis." (PMID 30174555, 2018). "In contrast, no increase in total CD4+ T cells was observed 1 week post sepsis induction in IL-7-treated septic mice, indicating a preferential expansion of Foxp3+CD25+ Tregs upon IL-7 treatment." (PMID 29466409, 2018). "Peripheral blood from sepsis survivors was collected 5–10 months after sepsis diagnosis and analysed for the frequency, and the absolute number of CD4+Foxp3+ T cells and serum concentration of IL-33 and IL-10 together with age- and sex-matched healthy volunteer blood donors (n=14)." (PMID 28374774, 2017). "Accumulated evidence has shown that a combination of Foxp-3, CTLA-4, TGF-βm+, and inhibitory cytokines (IL-10 and TGF-β) might serve as active markers for Tregs in the process of sepsis." (PMID 27835904, 2016). "It has been documented that the stability of Tregs includes the stability of Foxp-3 expression and negative immunoregulation in sepsis, which is crucially dependent on the demethylation status of the Foxp3-TSDR." (PMID 27835904, 2016). "The expressions of CTLA-4 and FOXP3 were significantly higher in patients with serious burns at all time points, and they were even higher in septic patients than those without sepsis on PBD 3 to 21 (P < 0.01)." (PMID 20064232, 2010). "During late-stage sepsis, TIGIT-expressing Foxp3+ Tregs exhibit enhanced suppressive function dependent on the IL-33/ST2/STAT6/M2 macrophage axis, suggesting that IL-33 or anti-TIGIT therapy may represent a promising strategy for the treatment of immunosuppressive sepsis." (PMID 40806563, 2025).
Sepsis (continued). "In addition, the expression of FOXP3, CTLA4, TIGIT, TNFRSF18, and IL2RA, key functional genes of Tregs, was increased in the E-SEP group, suggesting that the immunosuppressive effect of Tregs was enhanced in the elderly with sepsis." (PMID 38909272, 2024). "Measurement of CTLA-4 expression in the CD4+Foxp3− Tconv (CD4+ Tconv), CD4+Foxp3+ Treg (CD4+ Treg), and CD8+ T cell compartments of these mice after alcohol exposure and tamoxifen administration followed by CLP verified decreased CTLA-4 expression on both CD4+ Tconv and CD4+ Treg during sepsis." (PMID 38226924, 2024). "Mechanically, A2aR inactivation was associated with decreased frequencies and reduced function of Foxp3+ Tregs, as evidenced by Foxp3 and CTLA-4 expression and classical effector T-cell proliferative assays, suggesting Treg modulation is a potential protective mechanism against sepsis." (PMID 36148230, 2022). "Numerous studies of sepsis in adults have shown increases in percent Tregs and Treg activity (as measured through cytokine expression of IL-10 and TGF-β and as expression of CTLA-4 and FOXP3 on the cell surface) and implicate Tregs in adaptive immune suppression." (PMID 35958579, 2022). "Why are Foxp3+ Treg populations reduced during sepsis in the absence of CD43?" (PMID 30226896, 2018). "Moreover, Nrp‐1highCD4+CD25+ Tregs revealed primary negative immunoregulatory activity in reaction to sepsis, while administration of a recombinant version of Nrp‐1 polyclonal antibody markedly lowered the demethylation of Foxp3‐TSDR in a dose‐dependent manner under LPS stimulation." (PMID 34758202, 2022). "Our previous study suggested that recombinant Nrp-1 polyclonal antibody could decrease the demethylation of Foxp3-TSDR in the presence of LPS, thus, Nrp-1 could represent a new potential therapeutic target, at least via regulating the stability of Tregs, for the study of immune regulation in sepsis." (PMID 27835904, 2016). "Recently, another study shows that DEREG mice depleted of Foxp3+ T reg cells exhibit higher disease scores and mortality rates than non-depleted DEREG mice in the early-phase of severe sepsis, which similarly indicates that Foxp3+ T reg cells limit the hyper-inflammatory response." (PMID 26918357, 2016). "Importantly, depleting CD25+ Foxp3+ Treg erased the observed difference in mortality between WT and CD43-/- mice, while neutralizing IL-4 or adding back IFN-g-secreting Th1-like cells had no impact on sepsis survival in CD43-/- hosts." (PMID 30226896, 2018). "As previously observed in human and murine sepsis, this shift in the Treg/Teff ratio was probably due to the relative resistance of Tregs to apoptosis rather than to Treg expansion because the total number of CD4+Foxp3+ Tregs in the spleen was not significantly altered (data not shown)." (PMID 23724126, 2013).
breast tumor (61 papers, 2008 to 2025). "So the high rate of somatic mutations in breast tumors, its conserved sequence, and the regulation of important pathways make FOXP3 a very plausible candidate for a susceptibility gene in cancer." (PMID 24877082, 2014). "Therefore, we investigated TIL-expressing the B7-H1, PD-1, and FOXP3 molecules, in the microenvironment of human breast tumors and their possible association with the progression of the disease." (PMID 18294387, 2008). "Thus, we examined microvessel density, a surrogate for angiogenesis, and the number of tumor-associated macrophages (TAM) and FoxP3-positive T-regulatory cells in breast tumors by immunohistochemistry and assessed their relation to the race/ethnic background of the patients." (PMID 19225562, 2009). "Immunization with FGF-2 peptides decreased CD4+CD25+FOXP3+ Treg cells and suppressed tumor vascularization and promoted apoptosis in grafted breast tumor mice model." (PMID 39232704, 2024). "It has been proposed that Foxp3 acts as tumor suppressor in breast tumor cells, inhibiting the expression of protumoral molecules, including HER2 and VEGF, through binding and repression of their promoters." (PMID 37766222, 2023). "BRCA-mutated breast tumors are also characterized by the presence of TILs such as CD4+, CD8+, and FOXP3+ T lymphocytes." (PMID 38134458, 2023). "Since, the expressions of the gene signatures do not necessarily correlate with the actual number of cells, in our fifth approach, we directly evaluated the percentage of CD4+CD25+FOXP3+ Tregs from breast tumor patient-derived blood samples." (PMID 38038865, 2023). "The infiltration of Foxp3+ Tregs as well as the expression of Foxp3 in breast tumor cells, together with their subcellular localization, were proposed as prognostic markers for BRCA." (PMID 37766222, 2023). "Foxp3 inhibition with P60 enhanced chemosensitivity and reduced cell survival and migration in human and murine breast tumor cells." (PMID 37766222, 2023). "The regulatory T cell master transcription factor, Forkhead box P3 (Foxp3), has been detected in cancer cells; however, its role in breast tumor pathogenesis remains controversial." (PMID 37766222, 2023). "ART promotes CD8+ T cell activation by upregulating T-bet expression and decreases the percentage of Tregs by inhibiting Foxp3 expression in 4T1 breast tumor-bearing mice." (PMID 35785030, 2022). "In contrast to its effects on cytotoxic immune cells, SI-2 treatment significantly reduced the number of Foxp3+ cells in E0771 breast tumors in C57BL/6J mice compared to vehicle-treated mice." (PMID 36316775, 2022). "Our dual immunofluorescence staining revealed that SI-2 treatment also reduced the numbers of CD4-/Foxp3 + tumor cells in E0771 breast tumors." (PMID 36316775, 2022). "Compared to the control, SI-2 treatment significantly reduced the numbers of both CD4 + /Foxp3 + and CD4-/Foxp3 + cells in E0771 breast tumors." (PMID 36316775, 2022). "Conversely, the specific Treg cell marker FoxP3, necessary for immune-suppressive activity and immunological tolerance, was found to be enriched in cold breast tumors." (PMID 36139700, 2022). "We ablated or overexpressed FOXP3 in Treg cells and grew them on a breast tumor organoid bed to replicate the ex vivo TME to better understand the role of FOXP3 in CCR4 transcriptional activation." (PMID 35222362, 2022). "In line with this, TGF‐β produced by macrophages and regulatory T cells (FOXP3+) can promote epithelial–mesenchymal transition in breast tumor cells and thereby enhance tumor cell motility and intravasation." (PMID 34076969, 2021). "Before the advanced research on FOXP3 expression, it was thought to be expressed only in hematopoietic cells but now seems to be present in human tumors, particularly tumors of the breast." (PMID 34938323, 2021).
breast tumor (continued). "The findings are strongly supported by previous studies that have shown the association to be significantly lower in tumor grade and lymph node involvement in the breast tumor cells with positive FOXP3 expression." (PMID 34938323, 2021). "In the present study, the proportion of unstained TILs, the number of CD8+ TILs and the CFR increased, and the number of FOXP3+ TILs decreased in breast tumours after NAC." (PMID 30233820, 2018). "The numbers of CD4/CD8/Foxp3-positive cells were also significantly greater in the primary breast tumors than in the brain metastases (paired t-test, P < 0.05 [all categories])." (PMID 29262592, 2017). "In the present study, we disclosed the mechanisms of development and function of CD8+ Treg cells in breast tumor microenvironment, emphasizing the transcriptional regulation of their FOXP3 gene." (PMID 28487507, 2017). "Although Tregs are the major cell type expressing FOXP3, it has been demonstrated that tumor cells themselves can express this protein, such as those in pancreatic cancer, melanoma, and breast tumors." (PMID 28713192, 2017). "Here, we report the prevalence of CD8+ Treg cells in breast tumor microenvironment which expresses high-level of FOXP3." (PMID 28487507, 2017). "In tumor microenvironment, the CD8+CD25+FOXP3+ Treg population has found to be augmented with the advancement of breast tumor." (PMID 28487507, 2017). "In line with previous studies, we observed significant accumulation of CD4+FoxP3+ Tregs in breast tumors (13.4 ± 2.3%), compared with NT (2.9 ± 1.3%)." (PMID 28388539, 2017). "The numbers of CD4/CD8/Foxp3-positive cells were significantly higher in primary breast tumors than in brain metastases (paired t-test, P < 0.05 for all antibodies)." (PMID 29262592, 2017). "In our previous studies, we observed that breast tumor cells produce an abundant amount of TGFβ which can induce FOXP3 in the CD4+ naïve cell to differentiate them into Treg cells." (PMID 28487507, 2017). "Collectively, these data provide evidence of a new mechanism for breast tumor gene expression regulation, in which Runx1 and Foxp3 physically interact to control mammary epithelial cell gene expression fate." (PMID 26735887, 2016). "High levels of FOXP3+ T cells in breast tumours have been reported in both ductal carcinoma in situ (DCIS) and in much higher levels in invasive breast cancer." (PMID 27777963, 2016). "To achieve this goal, we investigated Runx1 and Foxp3 participation in the regulation of expression of two tumor associated genes, Rspo3 and GJA1, which are known modulators of breast tumor cell growth (positively and negatively, respectively)." (PMID 26735887, 2016). "Given that significant increase of CD4/CD8 ratio was observed in the late stage of breast tumor models, we therefore determined the alterations of Foxp3+CD4/CD8 T cell ratios in the different tumor developmental stages." (PMID 25968569, 2015). "In this study, we used specific immunohistochemistry with a widely used mouse monoclonal anti-human FOXP3 antibody to detect regulatory intratumoral and stromal TILs in breast tumor tissue." (PMID 25193543, 2014). "The results from this large study indicate that the prognosis of FOXP3+ regulatory lymphocyte infiltration into breast tumors differs with the expression status of ER, HER2 and concurrent CD8+ T-cell infiltration." (PMID 25193543, 2014). "To identify which bacterial taxa within the breast tumor microbiome are associated with TILs, we quantified the abundance of CD8+ and FoxP3+ TILs and retrieved expression levels of genes indicative of CD8+ T cell activation from our prior data, including GZMA/B/K and IFNG." (PMID 39554133, 2024). "Additionally, ACT with SRC-3 KO Tregs markedly reduced Foxp3+ cells in breast tumors compared to ACT with WT Tregs." (PMID 37253006, 2023).